HEPH (hephaestin)
Diseases named in the same sentence as HEPH in open-access papers (continued):
Sharing a sentence is not in itself a finding about the gene and the disease.
cancer (6 papers, 2015 to 2024). A tumor composed of atypical neoplastic, often pleomorphic cells that invade other tissues. "In addition, HEPH expression showed a very weak correlation with all infiltrating immune elements tested, while a strong positive correlation was found only with cancer associated fibroblasts (CAFs) and endothelial cells (ECs)." (PMID 34094919, 2021). "The hephaestin gene (HEPH) encoding the protein responsible for iron transport regulates the proliferation and apoptosis of cancer cells and facilitates reactive oxygen species (ROS) production." (PMID 38275400, 2024). "In silico analyses, based on UALCAN, Gene Expression Profiling Interactive Analysis (GEPIA) and Kaplan–Meier plotter bioinformatics, revealed a significant correlation between higher levels of HEPH expression and favorable prognosis, in both cancer histotypes." (PMID 34094919, 2021). "Moreover, in breast cancer HEPH expression has been shown to be down-regulated by the histone methyltransferase G9a, leading to changes in iron homeostasis that burst cancer growth." (PMID 34094919, 2021). "Through HEPH immune-labeling of LUAD and LUSC specimens, we clearly identified HEPH-expressing cells, characterized by the typical elongated spindle-shaped morphology of fibroblasts, enveloping some tumor nests in both LUAD and LUSC cancer histotypes." (PMID 34094919, 2021). "HEPH has been shown to act in concert with Ferroportin (FPN1), the only known mammalian iron exporter for non-heme iron, the mRNA down-regulation of which has been detected in several cancers, usually correlated to poor prognosis." (PMID 34094919, 2021). "Cancer cells in most of the analyzed LUAD specimens were totally lacking HEPH, even though a few clumps of neoplastic cells surrounded by stroma, the so-called tumor nests, positive to HEPH labeling, could be observed." (PMID 34094919, 2021).
tumor (5 papers, 2017 to 2023). "After adjusting the correlation by tumor purity, HEPH expression level was significantly correlated with all tested marker sets." (PMID 34094919, 2021). "Consistent with our in vitro results, we found that G9a depletion xenografts had higher levels of HEPH protein in the tumor tissue compared with the shcon tumors." (PMID 28819251, 2017). "Overall, the immune-labeling experiments, in concordance with the bioinformatics analysis, confirm the hypothesis that HEPH is expressed mostly by endothelial cells and stromal elements infiltrating the tumor microenvironment." (PMID 34094919, 2021). "To find out whether G9a regulates HEPH expression in vivo, we examined HEPH expression in tumor tissues from the G9a shcon and depletion xenografts." (PMID 28819251, 2017). "As acknowledged in tumor cells, proteins those raise intracellular iron contents (TfR-1, DMT1, hepcidin) are extensively upregulated, whereas those lower iron levels (FPN, hephaestin (HEPH)) are downregulated." (PMID 30591630, 2018). "Moreover, the tumor masses in LUSC and LUAD were also characterized by the presence of HEPH positive mesenchymal cells exhibiting spindle-shaped morphology, reminiscent of fibroblastic stromal component (LUAD and LUSC panels G)." (PMID 34094919, 2021).
HEPH also shares sentences with these, for which no sentence is quoted: pancreatitis (13 papers); acute pancreatitis (3); squamous cell carcinoma (2); Acute otitis media (1); adenocarcinoma (1); Anorexia (1); babesiosis (1); bladder urothelial carcinoma (1); breast invasive carcinoma (1); chronic pancreatitis (1); cognitive decline (1); colon adenocarcinoma (1); depression (1); diabetes (1); ductal breast carcinoma (1); euthyroid sick syndrome (1); glioblastoma (1); hereditary retinal degeneration (1); Hypercalcemia (1); Hypercholesterolemia (1); hyperlipidemia (1); infection (1); kidney chromophobe (1); mesothelioma (1); multiple sclerosis (1); myeloma (1); prostate adenocarcinoma (1); rectum adenocarcinoma (1); renal disease (1); renal failure (1).
A further 3 diseases each share a sentence with HEPH in 1 paper.